ALB (albumin)
Diseases named in the same sentence as ALB in open-access papers (continued):
Sharing a sentence is not in itself a finding about the gene and the disease.
thrombosis (continued). "High C-reactive protein to albumin ratio and D-dimer values were also predictive of thrombosis occurrence (p = 0.009, OR = 1.030, 95%CI 1.007‒1.052 and p = 0.002, OR = 1.016, 95%CI 1.006‒1.027, respectively)." (PMID 36028857, 2022). "Compared with other nephrotic diseases, membranous nephropathy (MN) is associated with the highest risk for developing venous thrombosis, especially RVT, even adjusted for gender, proteinuria, and serum albumin by multivariable analysis." (PMID 35380081, 2022). "Patients with venous thrombosis had significantly lower levels of albumin (23.95 ± 5.53 vs. 26.18 ± 6.59 g/L, p = .049)." (PMID 35380081, 2022). "In the univariate logistic regression, Ln anti-PLA2R antibody (OR: 1.340; p = .004), albumin (OR: 0.945; p = .050), CHOL (OR: 1.191, p = .006), and LDL (OR: 1.271, p = .006) were associated with venous thrombosis." (PMID 35380081, 2022). "Univariate analysis demonstrated that age > 60 years, hepatitis C, portal vein involvement (thrombosis), tumor size > 5 cm, AFP > 400 ng/mL, serum albumin, and CRP were risk factors for poor OS." (PMID 34067711, 2021). "Thrombosis prophylaxis is considered by almost half of the respondents in case albumin levels are below 20 g/l for over a month." (PMID 33532891, 2021). "The levels of APOA1 and ALB were significantly higher in patients with deep vein thrombosis than in healthy controls in un-targeted protein analysis of urine samples." (PMID 34768685, 2021). "The univariate analysis revealed that an age > 60 years, hepatitis C, portal vein involvement (thrombosis), a tumor size > 5 cm, alpha-fetoprotein (AFP) > 400 ng/mL, serum albumin, and C-reactive protein (CRP) were risk factors for poor OS." (PMID 34067711, 2021). "The diagnostic accuracies of ALB, AGR, fibrinogen, and ESR were nearly identical (75%) and lower than that of CRP (91.67%) in patients with venous thrombosis." (PMID 34172035, 2021). "She received antibiotic therapy (cefodizime, 20 mg/BID), sputum excretion, thoracic drainage, and anti-thrombosis therapy and was administered a protein-rich diet and albumin intravenous drip." (PMID 32569229, 2020). "Serum albumin concentration (p=0·43), thromboprophylaxis (p=0·17), and survival (p=0·45) were unrelated to deep vein thrombosis." (PMID 30709436, 2019). "Patients with coronary calcification scores above the median (n = 26) were older, had higher serum albumin levels, and had had more deep vein thrombosis and pulmonary embolism events compared with those below the median (n = 25)." (PMID 26269747, 2015). "Ascites albumin gradient and Doppler values lead to the diagnosis of thrombosis and the administration of high doses of anticoagulants is considered to be fundamental." (PMID 26579320, 2015). "In patients who developed deep vein thrombosis after laparoscopy, study variables such as tumor history, age, red blood cell count, blood pressure, D-dimer, hemoglobin, APTT, duration of surgery, albumin, and total protein were predictive of the development of deep vein thrombosis after laparoscopy." (PMID 40520687, 2025). "Moreover, researchers have looked into how serum albumin affects the development of deep vein thrombosis." (PMID 38167173, 2024). "In multivariate analysis, peak D-dimer level and C-reactive protein to albumin ratio were poor prognostic factors for thrombosis occurrence (OR = 1.022, 95%CI 1.007‒1.038 and OR = 1.025, 95%CI 1.001‒1.051, respectively), while thromboprophylaxis use was protective (OR = 0.199, 95%CI 0.061‒0.645)." (PMID 36028857, 2022). "No statistical association was seen between the presence of deep vein thrombosis and serum albumin concentration, despite previous studies suggesting such an association." (PMID 30709436, 2019). "Meta-analysis of the association of albumin and CRP with AVF stenosis and thrombosis." (PMID 27458819, 2016).
thrombosis (continued). "Patients with deep vein thrombosis (9.9%) differed significantly in age, history of tumor, hemoglobin, red blood cell counts, preoperative blood pressure, duration of the surgery, activated partial thromboplastin time, D-dimer, total protein, albumin, and calcium." (PMID 40520687, 2025). "The serum albumin and hemoglobin level of the PVT group were significantly lower than those of the non-thrombosis group (P < 0.05), and the Child-Pugh score and MELD score were higher than those of the non-thrombosis group (P < 0.05)." (PMID 34262917, 2021). "Serum albumin concentration or use of thromboprophylaxis were not related to presence of deep vein thrombosis." (PMID 30709436, 2019). "Of all the patients recruited, one did not satisfy the proteinuria/serum albumin criteria but had experienced two episodes of venous thrombosis and was symptomatic and hence was considered to be a candidate for treatment." (PMID 24289828, 2013). "The presence of thrombosis, however, did not correlate with any of the variables, such as age, LDH, stage, albumin, bulky disease, blood counts, lymphocyte-monocyte ratio (LMR), smoking, or body mass index (BMI)." (PMID 35706929, 2022). "Patients with venous thrombosis had significantly higher level of CHOL, low-density lipoprotein (LDL), D-dimer, and lower level of albumin than those without venous thrombosis (p = .025, p = .037, p < .001, p = .049, respectively)." (PMID 35380081, 2022). "Finally, patients with thrombosis exhibited abnormal results in values of platelets, CRP and albumin more frequently than non-VTE patients." (PMID 38676874, 2024).
asthma (62 papers, 2008 to 2026). "In model 4, controlling for confounders, a 1-unit increase in CPR was associated with a 1.05-fold increase in asthma, and a 1-unit increase in albumin (g/dL) was associated with a 0.8-fold decrease in asthma." (PMID 40259948, 2025). "A cohort study revealed a strong correlation between low serum albumin levels and an elevated risk of mortality in individuals with asthma." (PMID 39980673, 2025). "Respiratory infections and inflammatory diseases, such as asthma, can lead to reduced pulmonary function and increased capillary permeability, causing serum albumin to leak from the circulation into tissue fluid or to escape into the alveolar space." (PMID 38529288, 2024). "We used univariate and multivariate Cox proportional hazard models to investigate the connection between dietary protein intake, serum albumin and all-cause mortality in patients with asthma." (PMID 39026682, 2024). "Cohort studies can establish a causal association between dietary protein, serum albumin, and mortality in asthma patients." (PMID 39026682, 2024). "Finally, we find significant associations of genetically elevated GlycA with lung function and asthma susceptibility from bi-directional MR analyses, which is stronger than those of hsCRP and albumin." (PMID 38704398, 2024). "Our results from genetic analysis consistently suggested that low levels of serum albumin could be a useful indicator of lung function, risk of asthma and COPD." (PMID 38704398, 2024). "Elevated serum albumin levels provide potential protective effects for asthma patients through its antioxidant and anti-inflammatory properties." (PMID 39980677, 2025). "A decline in serum albumin levels indicates chronic inflammation and reduced antioxidant capacity, which is particularly evident in asthma patients." (PMID 39980677, 2025). "And another cross-sectional study in Australia has found that serum albumin is lower in people with more severe asthma and is positively related to lung function." (PMID 38835754, 2024). "According to a Turkish case-control study involving 40 asthma cases and 40 healthy subjects, there is a significant decrease in serum albumin concentration among bronchial asthma patients compared to controls." (PMID 38835754, 2024). "We applied both univariable and multivariable linear regression models to investigate the connection among asthma patients’ protein intake, serum albumin, and BEOC." (PMID 38835754, 2024). "And a prospective, multicenter study in Spain has demonstrated that the onset of asthma exacerbations is negatively correlated with serum albumin levels." (PMID 38835754, 2024). "So we used NHANES data to investigate the relationship of dietary protein intake, serum albumin levels, and mortality in persons with asthma to better understand their impact on asthma." (PMID 39026682, 2024). "We used data from the NHANES to explore the relationship of dietary protein, serum albumin, with mortality in individuals with asthma to better understand their impact on asthma." (PMID 39026682, 2024). "Future research endeavors should explore the potential influence of serum albumin in regulating and managing asthma while also elucidating potential mechanisms of action." (PMID 38835754, 2024). "Unstable asthma participants were more likely to be female, to have a higher BMI and lymphocyte, to have a lower PIR and albumin, and to have higher rates of asthma treatment." (PMID 39606578, 2024). "Our investigation gave unique insights into the connection of serum albumin with BEOC in patients with asthma." (PMID 38835754, 2024). "We showed a reverse linear connection of blood albumin levels and overall mortality in individuals with asthma using multivariate Cox hazard models and RCS." (PMID 39026682, 2024).
asthma (continued). "In fact, in this study, it was also observed that the albumin concentration in the asthma death group was lower compared to the survival group, possibly due to albumin's role in reflecting the nutritional status and reducing inflammation." (PMID 37803051, 2023). "The components PC14:0/16:0, PC16:0/18:2 (PC, phosphatidylcholine) and SP-A were higher among subjects with asthma, whereas albumin was lower." (PMID 33402401, 2021). "Asthma was significantly associated with an increase of PC14:0/16:0, PC16:0/18:2 and SP-A, but a decrease of albumin." (PMID 33402401, 2021). "Asthma was induced in mice using intranasal house dust mite or aerosol ova-albumin challenge, and chloroquine or quinine were tested in both prophylactic and treatment models." (PMID 28397820, 2017). "Significantly lower calcium, manganese, and albumin levels were found in children with asthma, while normal serum zinc levels were observed in both cases and controls." (PMID 26317027, 2014). "Children with asthma had reduced levels of plasma manganese, calcium, and albumin but raised level of selenium." (PMID 26317027, 2014). "This study contributes to the growing body of literature indicating that children with higher serum manganese, calcium, and albumin concentrations are less likely to have asthma." (PMID 26317027, 2014). "Our study showed that children with asthma had significantly lower mean calcium, manganese, and albumin levels when compared to controls." (PMID 26317027, 2014). "A correlation has been established between the severity of asthma and lower albumin levels." (PMID 39980673, 2025). "Moreover, polysensitization with elevated IgE levels to Can f 3 (albumin), Can f 4, and Can f 6 was more common in patients with asthma, while monosensitization to Can f 5 was more common in allergic rhinitis without asthma." (PMID 40234356, 2025). "PNI levels, which are evaluated through lymphocyte count and serum albumin, are associated with prognostic value in a variety of diseases, but the relationship between PNI and asthma remains unclear." (PMID 39980673, 2025). "This investigation proved a negative linear connection of serum albumin with all-cause mortality in asthma patients." (PMID 39026682, 2024). "However, there have been few investigations into the correlation between protein consumption, serum albumin, and asthma." (PMID 38835754, 2024). "This indicates that serum albumin could be a significant factor in predicting long-term outcomes for asthma patients." (PMID 39026682, 2024). "The investigation proved a negative linear connection of serum albumin with all-cause mortality in asthma patients." (PMID 39026682, 2024). "Meanwhile, some studies have reported the role of albumin in asthma, too." (PMID 38835754, 2024). "Moreover, it protected asthma-induced kidney and liver functions by increasing total protein and albumin and decreasing aspartate aminotransferase (AST), alanine aminotransferase (ALT), creatinine, urea, and uric acid levels." (PMID 37623736, 2023). "The ROC curve in this study revealed that the cut-off value for ACAG prediction of 30-d mortality in patients with asthma was 20.38 mmol/L, which may be due to differences in the disease spectrum with different albumin concentrations and anion concentration." (PMID 37803051, 2023). "The ratio of ITLN-1/albumin was significantly higher in SN-Asthma." (PMID 28775743, 2017). "Median baseline AMPs, IL-8 and albumin in nasal secretions according to asthma status." (PMID 26545199, 2015). "Bronchodilator activity of AET was studied on the histamine and acetylcholine aerosol induced bronchospasm in guinea pigs and bronchial hyperreactivity was studied on bronchoalveolar lavage fluid (BALF) in the egg albumin sensitized guinea pigs and by histopathological studies." (PMID 21607053, 2011).
asthma (continued). "Retrospectively, however, the data suggest that albumin conjugates may be uniquely suited as antigens in modeling isocyanate asthma, especially secondary to initial skin exposure." (PMID 21414210, 2011). "Furthermore, in animal models of TDI and HDI asthma, albumin conjugates have been shown to induce asthma-like airway inflammation and/or physiologic responses in previously (isocyanate) sensitized animals." (PMID 21414210, 2011). "We found that age, laboratory indicators (albumin, cystatin, white blood cell count, neutrophil count, lymphocyte percentage, mean hemoglobin, oxygen saturation and glucose), and major symptoms (fever, fatigue, cough, anorexia, diarrhea and asthma) were markedly correlated with the disease severity." (PMID 33332437, 2020). "However, this study did not detect the 27 kDa albumin, which was shown to be associated with Baker’s asthma or the alcohol-soluble gliadin proteins involved in celiac disease." (PMID 26124766, 2015). "Thus, while the pathogenesis of MDI (and other isocyanate-induced) asthma remains unclear, previous studies support an important role for chemical conjugation with albumin present in the airways." (PMID 21414210, 2011). "The new volatile type of TDI-human serum albumin conjugate could improve specific immunoglobulin E and immunoglobulin G bindings in enzyme-linked immunosorbent assay studies for identifying TDI-induced asthma patients." (PMID 23283297, 2008). "The investigation is the first and most extensive cross-sectional investigation to quantify the connection between protein intake, serum albumin, and BEOC in asthma patients, to the best of our knowledge." (PMID 38835754, 2024). "In total, we identified 60, 75, 47, 50, 16 and 7 shared loci of hsCRP with FEV1, FVC, FEV1/FVC ratio, PEF, asthma and COPD, respectively, and we also identified 32, 44, 8 and 2 of albumin with FEV1, FVC, asthma and COPD, respectively." (PMID 38704398, 2024). "The investigation employed three linear regression models and XGBoost model to investigate the potential link between protein intake, serum albumin levels, and blood eosinophil counts (BEOC) in patients with asthma." (PMID 38835754, 2024). "In another recent study that included 89 children with asthma, the combination of NLR, alanine aminotransferase ratio, and NLR–albumin ratio was suggested as a clinical biomarker for asthma exacerbation in children." (PMID 37176752, 2023). "Using Gromacs-2022.04, we simulated the molecular dynamics (MD) of a 100 ns protein-ligand complex for EGFR, ALB, MAPK8, ESR1, and SRC, respectively, which are typical core targets for allergic rhinitis and asthma." (PMID 37781715, 2023). "Overall, there were significant differences in age, albumin, eGFR, AST, creatinine, uric acid, sex, ethnicity, marital status, and history of asthma among ln transform SII quartiles (all p for trend <0.05)." (PMID 36172591, 2022). "Mice initially exposed to MDI via the skin, were subsequently exposed via the respiratory, to a water soluble derivative of MDI (mouse albumin conjugates), in an adaptation of our murine HDI asthma model." (PMID 21414210, 2011). "Studies have demonstrated that compared to the non-asthmatic population, individuals with asthma have lower serum albumin levels." (PMID 40259948, 2025). "A study observed an inverted U-shaped relationship between serum albumin and bronchial eosinophilic inflammation in asthma (BEOC), indicating a potential connection between the overall nutritional state and immune system alterations in asthma patients." (PMID 40259948, 2025). "Past studies indicated a negative relationship between albumin and the proportion of eosinophils, important inflammatory cells in asthma attacks." (PMID 39722824, 2024). "Serum albumin levels are reduced in various conditions, thus it is a non-specific and prognostically relevant marker of asthma." (PMID 39026682, 2024).